GTPBP1 (GTP binding protein 1)
Description:
GTPase that plays a role in the elongation phase of protein synthesis by forming ternary complexes with GTP and aminoacyl-transfer RNAs (aa-tRNAs), and delivering aa-tRNAs to the ribosomal A site in a GTP-dependent manner. Is also able to deliver deacylated tRNA to the A site. Additionally, it is involved in RNA quality control; after GTP hydrolysis, which is not immediately followed by rapid peptide bond formation, GTPBP1 likely retains aa-tRNA in the A site and promotes exosomal degradation of faulty mRNAs engaged in 80S elongation complexes. Plays a role in the regulation of circadian mRNA stability (By similarity).
Synonyms: GP-1; GP1; HSPC018; NEDFET1
Tractability: PROTAC: ubiquitination databases record sites on it; its protein half-life has been measured.
Gene: Protein-coding gene on chromosome 22 (38,705,742 to 38,738,299, forward strand). Ensembl gene ENSG00000100226.
Subcellular location: Cytoplasm
Subcellular location (Human Protein Atlas): Cytosol; Golgi apparatus; Nuclear bodies
Gene Ontology:
Molecular function: alpha-aminoacyl-tRNA binding; GTP binding; GTPase activity; protein binding; RNA binding; translation elongation factor activity; tRNA binding
Biological process: cytoplasmic translation; RNA surveillance; GTP metabolic process; immune response; positive regulation of mRNA catabolic process; signal transduction; translational elongation
Cellular component: membrane; cytoplasm; cytoplasmic exosome (RNase complex); cytosol
Genetic constraint (gnomAD): Loss-of-function variants: 16 observed, 38.53 expected, observed/expected ratio (o/e) 0.42, 90% interval 0.28 to 0.63. The upper end of that interval is the gene's LOEUF score, 0.63, which puts it in group 2 of 6, group 1 being the genes least tolerant of losing a copy. Missense variants: 517 observed, 736.19 expected, observed/expected ratio (o/e) 0.7, 90% interval 0.65 to 0.75. Synonymous variants: 300 observed, 294.62 expected, observed/expected ratio (o/e) 1.02, 90% interval 0.93 to 1.12.
Homologues: Orthologues: chimpanzee GTPBP1 (100% identical), macaque GTPBP1 (99% identical), dog GTPBP1 (98% identical), rat Gtpbp1 (97% identical), guinea pig GTPBP1 (97% identical), mouse Gtpbp1 (97% identical), pig GTPBP1 (95% identical), rabbit GTPBP1 (94% identical), tropical clawed frog gtpbp1 (85% identical), zebrafish gtpbp1 (79% identical), zebrafish gtpbp1l (76% identical), Drosophila melanogaster Dgp-1 (59% identical), and 1 more. Paralogues in human: GTPBP2 (41% identical), EEF1A1 (17% identical), EEF1A2 (16% identical), GSPT1 (16% identical), GSPT2 (16% identical), TUFM (15% identical), MTIF2 (14% identical), EIF5B (14% identical), HBS1L (14% identical), EFL1 (13% identical), EFTUD2 (11% identical), GFM1 (11% identical), and 6 more.
Diseases named in the same sentence as GTPBP1 in open-access papers:
GTPBP1 is named in the same sentence as 57 diseases in open-access papers, as found by Europe PMC text mining. Sharing a sentence is not in itself a finding about the gene and the disease. The quoted sentences say what the papers report.
epilepsy (3 papers, 2020 to 2024). A brain disorder characterized by episodes of abnormally increased neuronal discharge resulting in transient episodes of sensory or motor neurological dysfunction, or psychic dysfunction. "The clinical syndrome associated with bi-allelic GTPBP1 or GTPBP2 variants can be defined as a complex syndromic neurodevelopmental disorder associated with severe neurodegeneration, epilepsy, choreiform movement disorder, and ectodermal abnormalities, with pathognomonic craniofacial features." (PMID 38118446, 2024).
Ataxia (1 paper, 2020). Ataxia refers to impaired coordination of voluntary muscle movement. "Like B6J-Gtpbp2-/- mice, B6J.Gtpbp1-/- mice were indistinguishable from littermate controls at 3 weeks of age, developed overt ataxia by 6 weeks, and died by 8 weeks of age." (PMID 33186095, 2020).
microcephaly (1 paper, 2024). A congenital or acquired developmental disorder in which the circumference of the head is smaller than normal for the person's age and sex. "Individuals with bi-allelic GTPBP1 or GTPBP2 variants presented with microcephaly, profound neurodevelopmental impairment, pathognomonic craniofacial features, and ectodermal defects." (PMID 38118446, 2024).
uveal melanoma (1 paper, 2023). A melanoma derived from melanocytes of the uveal tract. "To verify our computational findings, we tested the mRNA expression level of CCL18, CXCL8, GTPBP1, JAG2, PRELID1 and PTGER4 in uveal melanoma cell lines: M17, M23 and SP6.5 and normal uveal epithelial cell: Um95." (PMID 36597071, 2023).
infection (70 papers, 2007 to 2026). The state of being infected such as from the introduction of a foreign agent such as serum, vaccine, antigenic substance or organism. "LTβR−/− animals did not exhibit such a distinct increase p.i.; GTPBP1 expression levels were only moderately increased during the course of infection." (PMID 28845089, 2017).
tumor (6 papers, 2019 to 2026). "Through interaction with DIS3 as a possible tumor suppressor, GTPBP1 can progress tumor progression in ATLL." (PMID 35041720, 2022).
cancer (5 papers, 2013 to 2022). A tumor composed of atypical neoplastic, often pleomorphic cells that invade other tissues. "In this study, we conducted a pan-cancer exploration of GTPBP1-10, including expression analysis, survival analysis, immune infiltration analysis, methylation correlation analysis, and prediction of GTPBP4-related transcription factors." (PMID 35320117, 2022). "Subsequently, we explored the expression of GTPBP1-10 in cancer by way of a paired t-test and plotted the survival curve using KM and univariate Cox regression analysis to explore the relationship between GTPBP1-10 and the prognosis of cancer." (PMID 35320117, 2022). "Our study identified a new class of markers of significance to 18 types of cancer: GTPBP1-10." (PMID 35320117, 2022). "Moreover, GTPBP1-10 were differentially expressed in different immune subtypes and correlated with the immune score, stromal score, RNASS and DNASS of various cancers." (PMID 35320117, 2022). "Most of the GTPBP proteins displayed a negative correlation with the immune score in cancer, while GTPBP1, 2 and 8 showed a positive correlation with the immune score in cancer." (PMID 35320117, 2022).
neurodevelopmental disorder (1 paper, 2024). A behavioral and cognitive disorder with onset during the developmental period that involves impaired or aberrant development of intellectual, motor, or social functions. "We report molecular, clinical, and cellular findings in 20 affected individuals from 16 families affected with severe neurodevelopmental disorders and bi-allelic variants in GTPBP1 or GTPBP2." (PMID 38118446, 2024).
GTPBP1 also shares sentences with these, for which no sentence is quoted: viral infection (10 papers); Ebola (8); Lassa fever (5); Stroke (4); hemorrhagic fever (3); ischemic stroke (3); acute myocardial infarction (2); Anxiety (2); arenavirus infection (2); COVID-19 (2); dyslipidemia (2); renal fibrosis (2); Sepsis (2); acute coronary syndrome (1); Alzheimer disease (1); antiphospholipid syndrome (1); atherosclerosis (1); autism spectrum disorder (1); autoimmune disease (1); bacterial infection (1); borna disease (1); breast carcinoma (1); colitis (1); colon tumor (1); cryptosporidiosis (1); dementia (1); depression (1); diabetes (1); fragile X syndrome (1); gastric cancer (1).
A further 19 diseases each share a sentence with GTPBP1 in 1 paper.